RNY4P30 (RNY4 pseudogene 30)
Gene: Miscellaneous RNA gene on chromosome 13 (49,889,634 to 49,889,728, reverse strand). Ensembl gene ENSG00000222148.
Homologues: Orthologues: chimpanzee Y_RNA (99% identical). Paralogues in human: RNY4P29 (98% identical), RNY4P9 (92% identical), Y_RNA (86% identical), RNY4 (83% identical), RNY4P6 (82% identical), Y_RNA (82% identical), RNY4P19 (81% identical), Y_RNA (81% identical), RNY4P13 (80% identical), RNY4P25 (80% identical), RNY4P7 (80% identical), Y_RNA (80% identical), and 84 more.